MMP2 (matrix metallopeptidase 2)
Diseases named in the same sentence as MMP2 in open-access papers (continued):
Sharing a sentence is not in itself a finding about the gene and the disease.
type 1 diabetes (19 papers, 2008 to 2025). "Increased circulating levels of MMP‐2 were associated with microangiopathy in 25 children and adolescents with type 1 diabetes (median age, 11 years; range, 8‐12 years) compared with 19 controls (median age, 12 years; range, 11‐13 years)." (PMID 33855203, 2021). "Higher plasma MMP‐2 levels in type 1 diabetes patients were further associated with cardiovascular events and all-cause mortality in a 12-year follow-up study." (PMID 31932967, 2021). "In the present study we evaluated the expression of the MMP-2 isoforms in an experimental model of Type I diabetes mellitus and demonstrate an association between NTT-MMP-2 isoform expression, mitochondrial injury and systolic dysfunction." (PMID 31461499, 2019). "Despite these limitations, our results showed largely consistent results throughout the three different studies with regard to the associations between MMP-1, MMP-2 and PP in individuals with type 1 diabetes." (PMID 29070037, 2017). "In this study with type 1 diabetic patients, plasma MMP-2, MMP-3, MMP-10 and TIMP-1 levels are associated with macro- and microvascular complications and these associations were largely independent of LGI and ED." (PMID 25848912, 2015). "Further, plasma MMP-2 levels and its activity are significantly higher in type-1 diabetic patients compared with control subjects, and urinary MMP-2 values are positively associated with renal hyperfiltration and albuminuria in these diabetic patients as well." (PMID 25143788, 2014). "The significant differences seen in MMP‐2 levels and activity between participants with type 1 diabetes and microangiopathic complications versus controls persisted for 5 years (P < .001 for both)." (PMID 33855203, 2021). "In patients with type 1 diabetes followed for a median of 12 years, higher plasma MMP-2 levels are associated with incident CVD and higher plasma MMP-1, MMP-2, MMP-3 are associated with all-cause mortality." (PMID 28446168, 2017). "In individuals with type 1 diabetes, MMP-1 (inversely) and MMP-2 and -3 (both positively) were associated with markers of arterial stiffening (PP and cfPWV)." (PMID 29070037, 2017). "Blood samples from patients with type 1 diabetes contained higher concentrations of MMP-2 and MMP-9 compared to healthy controls." (PMID 22363890, 2011). "The serum levels of both MMP-9 and MMP-2 were significantly higher in subjects with type 1 diabetes, compared to controls (p = 0.016 and p = 0.008 respectively)." (PMID 19758433, 2009). "Metalloproteinase-2 and -9 (MMP-2/9), whose activities are known to be increased in the plasma of type 1 diabetic patients, have the potential for claudin-5 degradation, while caveolae-mediated internalization of claudin-5 can be promoted by the pro-inflammatory cytokine CCL-249." (PMID 35264685, 2022). "In addition, increased circulatory MMP-9, as well as MMP-2, has been reported in older subjects with type 1 diabetes." (PMID 19758433, 2009). "We have recently shown that the levels of MMP-2 and MMP-9 were higher in serum from subjects with type 1 diabetes than in controls, whereas the levels of tissue inhibitors of metalloproteinases (TIMPs) were not affected." (PMID 22363890, 2011). "We further determined the concentrations of MMP-2 and MMP-9 in samples from subjects with type 1 diabetes and controls using ELISA." (PMID 19758433, 2009). "Interestingly, IL-21 activity is increased in Helicobacter pylori infection, leading to higher production of matrix metalloproteinases MMP2 and MMP9, and MMP2 and MMP9 have been shown to be upregulated in Type 1 diabetes." (PMID 18773086, 2008). "Interestingly, higher plasma levels of MMP-2 and -10 have been observed in patients with type 1 diabetes compared to non-diabetic controls." (PMID 28446168, 2017).
gastric tumor (18 papers, 2014 to 2023). "After culture for 7 days, qRT-PCR and WB assays showed that the expression of POSTN, FAP, MMP2 and PDGFα in the gastric tumour cell exosome-treated group was gradually increased compared with that in the MSC control group." (PMID 37199594, 2023). "Previous studies have shown that UMB inhibits gastric tumor growth and migration through inhibition of MMP2 and MMP9." (PMID 34335844, 2021). "Equally, the immunoreactivity of MMP-2 is greater in gastric tumors with metastasis compared to primary gastric tumors." (PMID 24669030, 2014). "Bigelovin, tanshinone II-A, antartina, cinobufacini, curcumin, honokiol, and peperomin E showed anti-metastatic effects via the modulation of MMP-2/9, TIMPs, and N-cadherin under various experimental models of transplanted colon/gastric tumor tissues and cytolytic T cells in blood." (PMID 37444525, 2023). "Furthermore, it has been shown that MMP-2 production and activation directly correlates with invasion of tumor cells and lymphatic permeation in stomach tumors." (PMID 29721201, 2018). "Meanwhile, mRNA levels of NF-kB downstream metastasis-related genes including Vimentin, MMP-2, MMP-9, VEGF, ICAM-1 and VCAM-1 were significantly enhanced in the primary gastric tumors." (PMID 30728051, 2019). "We also note that the expression of several angiogenesis-related genes (Cxcl1, Cxcl2, Mmp2, Mmp9, and Vegf) was comparable among gastric tumor and non-tumor tissues from 3mo and 6mo gp130F/F and gp130F/F:Nlrp3-/- mice." (PMID 35299732, 2022). "For example, NIR/PET probes sensitive for MMP-2, -9 and -13 were used for detection of tumors in a mouse cancer model, a FRET/SPECT probe designed for MMP-2 and was used for in vivo imaging of metastatic lymph nodes and a FRET/MRI probe was developed for MMP-2 and bimodal imaging of gastric tumors." (PMID 33802262, 2021). "Moreover, NDV-D90 appeared to reduce gastric tumor vascularization, possibly through suppression of vascular endothelial growth factor A (VEGF-A) and Matrix Metallopeptidase 2 (MMP-2)." (PMID 28388537, 2017). "Thus, NDV-D90 appeared to reduce gastric tumor vascularization, possibly through suppression of VEGF-A and MMP-2." (PMID 28388537, 2017).
head and neck cancer (18 papers, 2013 to 2024). A primary or metastatic malignant neoplasm affecting the head and neck. "In numerous reports regarding head and neck cancers, the present correlations are emphasized between the changes in the expression of MMP-2, MMP-9, TIMP-1, and TIMP-2 with tumor progression or its clinical stage." (PMID 31223594, 2019). "Indeed, using recombinant human IL-8 as a treatment of head and neck cancer cells, their Western blot analyses revealed a decrease in the expression of E-cadherin and an increase in the expression of MMP2, MMP9, and vimentin compared to the untreated conditions." (PMID 37628994, 2023). "MMP-2 is well known not only for its degradation of ECM, but also as a tumor marker for poor prognosis of head and neck cancer." (PMID 33096744, 2020). "For head and neck cancers, MMP-1, MMP-2, MMP-9 and membrane type-1 MMP were constantly observed overexpressed in the tumor tissues and were considered associated with the development and progression of cancer." (PMID 28427180, 2017). "For head and neck cancers, MMP-1, MMP-2, MMP-9 and membrane type-1 MMP have been found overexpressed in the tumor tissues and been associated with cancer progression." (PMID 25423087, 2014). "Microarray analysis reveals that MMP1 and MMP2 are the most significantly upregulated genes in NPC biopsies, compared with lymphohyperplasia, adenoid tissues, and head and neck cancer." (PMID 24955581, 2014). "Similarly, another recently published study has shown that dehydrocrenatidine prevents head and neck cancer cell motility, migration, and invasion by inhibiting ERK1/2 and JNK1/2 phosphorylation and reducing MMP-2 expression." (PMID 35455398, 2022). "In a clinical context MMP2 and MMP9 overexpression may be helpful markers in diagnosing head and neck cancer metastasis." (PMID 28963552, 2017). "The strongest effect of ascorbate dependent downregulation of HIF-1α target genes expression was also observed for CA9 in head and neck carcinoma cell line 22B (more than 75-fold decrease in CA9 compared to a 25-fold decrease for GLUT3 and a 50-fold decrease for MMP-2)." (PMID 29100428, 2017).
multiple myeloma (18 papers, 2000 to 2025). "In multiple myeloma, a number of MMPs have been implicated in disease progression, most notably MMP-2 and MMP-9." (PMID 28241871, 2017). "We have also shown that MMP-2 can be specifically inhibited in the multiple myeloma-bone microenvironment underscoring the feasibility of selectively targeting MMPs in a tissue specific manner." (PMID 28611279, 2017). "For example, MMP-2 is highly expressed in bone marrow aspirates of multiple myeloma patients and the co-culture of myeloma cells with bone marrow stromal cells results in enhanced activation of the enzyme." (PMID 28611279, 2017). "Studies also show that latent MMP-2 can be activated in the co-cultures of multiple myeloma and bone marrow stromal cells." (PMID 28611279, 2017). "To address this, we created highly specific “bone-seeking” MMP-2 inhibitors (BMMPIs) to target the multiple myeloma-bone microenvironment." (PMID 28611279, 2017). "BMMPIs are structurally based on bisphosphonates ensuring that these agents target sites of multiple myeloma-induced osteolysis, while limiting the potential off-target effects of systemic MMP-2 inhibition." (PMID 28611279, 2017). "Using immunofluorescence and CD138 to identify the myeloma cells, we observed that the majority of multiple myeloma cells in the bone marrow biopsies were positive for MMP-2." (PMID 28611279, 2017). "Using in vivo models of multiple myeloma (5TGM1, U266), we examined the impact of MMP-2 inhibition on disease progression using BMMPIs." (PMID 28611279, 2017). "Matrix metalloproteinase-2 (MMP-2) is associated with cancer and is significantly overexpressed in the bone marrow of myeloma patients." (PMID 28611279, 2017). "Taken together, these data provide rationale for the inhibition of MMP-2 as a potential therapeutic approach for the treatment of multiple myeloma." (PMID 28611279, 2017). "Analysis of conditioned media from multiple myeloma cell lines show that MMP-2 is expressed at the protein level but the majority of the enzyme is in a latent state." (PMID 28611279, 2017). "For example, SC-964 (a broad spectrum inhibitor of MMP-2, -3, 8, -9 and -13) significantly reduced 5TMM mouse multiple myeloma burden, osteolytic lesions and angiogenesis." (PMID 28611279, 2017). "Further, ex vivo analysis of bone marrow from multiple myeloma-bearing animals demonstrate the selective inhibition of MMP-2 activity in the bone microenvironment in the ML104, compared to zoledronate treated animals." (PMID 28611279, 2017). "Given the possible roles for tumor and bone derived MMP-2 in driving the progression of skeletal malignancies we examined human multiple myeloma biopsies (n = 10) for the presence of MMP-2." (PMID 28611279, 2017). "We would therefore predict that MMP-2 in the in vivo multiple myeloma-bone microenvironment is in an active state, which is supported by our ex vivo MMP-2 activity assays using bone marrow supernatants isolated from myeloma-bearing mice." (PMID 28611279, 2017). "Both resveratrol and ω-3 fatty acids can independently suppress MMP-2 protein activity and RNA expression in patients with multiple myeloma." (PMID 26153682, 2015). "In myeloma, re-expressing wild-type PTEN in PTEN-deficient cells represses proliferation and invasion by downregulating FAK, MMP2 and MMP9 expression and activity, indicating that HPSE and PTEN are targeting expression of the same proteins but in opposite ways." (PMID 32899927, 2020). "Based on the detection of MMP-2 in the myeloma-bone microenvironment and the role of the enzyme in driving cancer progression, we hypothesized MMP-2 inhibition may be a potential target for the treatment of the disease." (PMID 28611279, 2017). "While the inhibition of MMP-2 had beneficial effects in reducing tumor burden and protecting against myeloma induced bone disease, targeting other individual MMPs known to play a role in multiple myeloma progression may be of benefit." (PMID 28611279, 2017).
multiple myeloma (continued). "In vitro studies suggest that myeloma-derived MMP-7 can activate stromal MMP-2, however the in vivo role of MMP-7 in myeloma pathogenesis thus far is unknown." (PMID 28241871, 2017). "Additionally, we have shown that MMP-2 can be specifically inhibited in the multiple myeloma-bone microenvironment, underscoring the feasibility of developing targeted and tissue selective MMP inhibitors." (PMID 28611279, 2017). "We posit that the reduced MMP-2 activity in combination with reduced osteoclast activation limits bone matrix remodeling and the availability of growth factors and cytokines that can drive multiple myeloma growth." (PMID 28611279, 2017). "MMP-2 is widely expressed in tissues throughout the body and therefore targeted inhibition of the enzyme for the treatment of multiple myeloma could potentially result in systemic toxicity." (PMID 28611279, 2017). "While BMMPIs did not impact multiple myeloma cell line survival significantly in vitro, we expected that they may be effective in the context of the in vivo bone microenvironment given the combined presence of MMP-2 in the multiple myeloma and host compartments." (PMID 28611279, 2017). "Based on this, we will conduct a more comprehensive analysis and discussion on the exact roles of MMP-2 and MMP-9 in multiple myeloma, as well as their potential clinical implications." (PMID 37823051, 2023). "Zoledronate and the non-MMP-2 selective BMMPI, ML111, also showed modest effects on multiple myeloma cell viability." (PMID 28611279, 2017). "Using an MMP-2 specific quenched fluorescent substrate, we demonstrated that ML104 significantly reduced MMP-2 activity in the multiple myeloma-bone microenvironment compared to either the control or zoledronate groups." (PMID 28611279, 2017). "Results show that the highly selective MMP-2 based inhibitors (ML104 and ML115) impacted multiple myeloma cell line viability but only at higher concentrations." (PMID 28611279, 2017). "It has recently been demonstrated that the forced expression of HOXB7 in multiple myeloma induces the up-regulation of VEGFA, FGF2, MMP2 and PDGFA, and the down-regulation of thrombospondin 2, a profile largely shared by RC." (PMID 25115389, 2014). "In situ hybridization analysis revealed that lymphoblastic leukemia B cells (SBcell line), multiple myeloma (MM) cells (U266 cell line) and lymphoblastic leukemia T cells(CEM and Jurkat cell lines) express constitutively the mRNA for MMP-2 and/or MMP-9." (PMID 11097203, 2000). "Corroborating our observations, MMP-2 is mostly produced by multiple myeloma patients’ bone marrow stroma cells rather than the malignant plasma cells." (PMID 38674139, 2024). "This review focuses on the role of MMP-1, MMP-2, MMP-7, MMP-9, MMP-13, MMP-14, and MMP-15 and the four types of TIMPs in the invasion of myeloma cells, angiogenesis, osteolytic osteopathy, to offer some novel perspectives on the clinical diagnostics and therapeutics of MM." (PMID 37823051, 2023). "Combination of BMMPIs that target other MMP family members expressed in the bone microenvironment such as MMP-2 and MMP-9 therefore may act synergistically with bortezomib for the treatment of multiple myeloma." (PMID 28611279, 2017). "Analysis of publically available datasets (GSE47552) examining gene expression in CD138+ isolated myeloma cells at various stages of disease progression did not demonstrate changes in MMP-2." (PMID 28611279, 2017). "Given the contribution of MMP-2 to the progression of several skeletal malignancies, we posit that the combined MMP-2 inhibition and anti-osteoclast activity of ML104 explains why ML104 and zoledronate behave similarly in vivo in preventing multiple myeloma progression." (PMID 28611279, 2017).
multiple myeloma (continued). "While we demonstrate that MMP-2 is expressed in the multiple myeloma-bone microenvironment of human specimens, public database analyses did not reveal a correlation between MMP-2 and multiple myeloma stage at the gene expression level in CD138 isolated cells." (PMID 28611279, 2017). "In contrast, the role of MMP-7 is relatively unknown in myeloma, and is currently limited to the expression of MMP-7 by human myeloma cells, with resultant in vitro activation of MMP-2." (PMID 28241871, 2017). "Interestingly, Bortezomib (a proteasome inhibitor used in humans as a therapeutic agent for multiple myeloma) has been shown to elicit an anti-fibrosis effect through a dual activity: an increase in MMP1 and MMP2 mRNA and proteins and a decrease in collagen 1a mRNAs and proteins." (PMID 35203262, 2022). "In addition, another study on multiple myeloma patients revealed that MMP-2 and MMP-9 are secreted in higher amounts and are not balanced by inhibitors of TIMPs." (PMID 31474817, 2019). "Based on evidence that MMP-2 is expressed in the bone marrow of myeloma patients and known roles for MMP-2 in the progression of skeletal malignancies, we hypothesized that inhibiting MMP-2 in myeloma would be an effective therapeutic strategy to prevent disease progression." (PMID 28611279, 2017).